ZNF628 (zinc finger protein 628)
Description:
Transcriptional activator. Binds DNA on GT-box consensus sequence 5'-TTGGTT-3'. Plays a role in spermiogenesis.
Synonyms: ZEC; Zfp628
Tractability: No criterion of Open Targets' tractability assessment is met for any kind of drug.
Gene: Protein-coding gene on chromosome 19 (55,476,617 to 55,484,487, forward strand). Ensembl gene ENSG00000197483.
Subcellular location: Nucleus
Subcellular location (Human Protein Atlas): Nucleoplasm
Gene Ontology:
Molecular function: protein binding; DNA-binding transcription factor activity, RNA polymerase II-specific; RNA polymerase II cis-regulatory region sequence-specific DNA binding; DNA binding; DNA-binding transcription factor activity
Biological process: regulation of DNA-templated transcription; regulation of transcription by RNA polymerase II; spermatogenesis
Cellular component: nucleus
Genetic constraint (gnomAD): Loss-of-function variants: 4 observed, 1.74 expected, observed/expected ratio (o/e) 2.3. That is too few expected variants to judge how well the gene tolerates losing a copy. Missense variants: 1,610 observed, 1,274.1 expected, observed/expected ratio (o/e) 1.26, 90% interval 1.21 to 1.32. Synonymous variants: 860 observed, 611.8 expected, observed/expected ratio (o/e) 1.41, 90% interval 1.33 to 1.49.
Homologues: Orthologues: chimpanzee ZNF628 (99% identical), pig ZNF628 (86% identical), dog ZNF628 (86% identical), mouse Zfp628 (85% identical), rat Zfp628 (84% identical), guinea pig ZNF628 (52% identical), tropical clawed frog znf628 (46% identical). Paralogues in human: ZNF629 (20% identical), ZNF189 (20% identical), ZNF229 (20% identical), ZNF132 (20% identical), ZNF235 (20% identical), ZNF7 (19% identical), ZNF224 (19% identical), ZNF227 (19% identical), ZNF841 (19% identical), ZNF484 (19% identical), ZNF30 (19% identical), ZNF836 (19% identical), and 164 more.
Diseases named in the same sentence as ZNF628 in open-access papers:
ZNF628 is named in the same sentence as 2 diseases in open-access papers, as found by Europe PMC text mining. Sharing a sentence is not in itself a finding about the gene and the disease.
ZNF628 shares sentences with these, for which no sentence is quoted: Alzheimer disease (1 paper); Infertility (1).